NGF (nerve growth factor)
Diseases named in the same sentence as NGF in open-access papers (continued):
Sharing a sentence is not in itself a finding about the gene and the disease.
prostate carcinoma (continued). "To identify the regulatory mechanisms between ZBTB46-NGF signaling and NEPC differentiation, we examined ZBTB46 and NGF expressions in gene signatures of NEPC in TCGA prostate cancer dataset by a GSEA." (PMID 33398073, 2021). "The NGF was reported to promote prostate cancer cell metastasis, yet the mechanisms and functions of NGF in NEPC differentiation have not been clearly elucidated." (PMID 33398073, 2021). "Although the authors did not explain the mechanism of NGF-mediated AR re-expression in prostate cancer cells, NGF administration can downregulate DNA methyltransferases in other cells." (PMID 33420371, 2021). "A neutralizing anti-NGF antibody has been used to reduce the pain related to autoimmune diseases and was successfully tested in preclinical models of prostate cancer." (PMID 34268306, 2021). "In prostate cancer, the NGF stimulates NTRK1 downstream of p38-MAPK activation to promote cell migration, invasion, and metastasis." (PMID 33398073, 2021). "In our study, we established a link between NGF promotion of neuroendocrine differentiation via CHRM4 after the development of resistance to ADT in prostate cancer." (PMID 33398073, 2021). "Recent reports have shown that nerve growth factor (NGF) promotes EMT in prostate cancer cells via activation of the NGF tyrosine kinase receptor, tropomyosin receptor kinase A." (PMID 31968685, 2020). "Another early investigation on that topic confirmed the involvement of the CB1 receptor in the AEA-induced inhibition of nerve growth factor-activated breast and prolactin-activated prostate cancer cell proliferation." (PMID 31143113, 2019). "NGF, in its precursor or mature form, has been strongly implicated in PNI and neoneurogenesis in prostate cancer." (PMID 31812953, 2019). "Similar to previous findings in prostate cancer, cancer cell nests containing both NGF and NTRK1 suggested an important autocrine tumor maintenance function of this system in HNSCC." (PMID 29904026, 2018). "In prostate cancer, the development of NGF/NTRK1 or BDNF/NTRK2 autocrine signaling pathways is an escape mechanism, from both the androgen control and the paracrine dependence of stromal cells produced neurotrophins." (PMID 29904026, 2018). "In PC3 prostate cancer cells, which express relatively high levels of both CD44 and TrkA, NGF stimulation resulted in the association of TrkA with CD44 at the plasma membrane, as demonstrated using the PLA signal of TrkA/CD44." (PMID 25840418, 2015). "Progression of prostate cancer is accompanied by modifications in the expression of neurotrophins, including NGF, and neurotrophin receptors." (PMID 24212627, 2011). "Here we will discuss the current literature regarding the role of NGF in cell death and survival signaling in breast and prostate cancers." (PMID 24212627, 2011). "In fact, strategies that are aimed at inhibiting NGF signaling are already in clinical trials for the treatment of prostate cancer." (PMID 24212627, 2011). "Here we will describe the role of NGF in cell death and survival signaling with a particular focus on breast and prostate cancers, since most advances in this area have been made in these cancers." (PMID 24212627, 2011). "Canonical pathways triggered by interactions of the NGF with other receptors in neuroendocrine differentiation of prostate cancer are unknown." (PMID 33398073, 2021). "The present study, together with our previous findings in prostate cancer, further points to the relevance of NGF signaling in “gender-related cancers” and paves the way for new therapeutic opportunities in the clinical management of TNBC patients, who often exhibit or develop drug resistance." (PMID 34268306, 2021). "We also found that NGF overexpression or NGF-knockdown in prostate cancer cells, respectively, increased or decreased ZBTB46 expression, suggesting that activated NGF may play a positive feedback role in regulating ZBTB46." (PMID 33398073, 2021).
prostate carcinoma (continued). "We hypothesized that ZBTB46 upregulates NGF expression in prostate cancer cells by acting as a transcriptional activator and binding to a ZBTB46-binding element (ZBE) in the NGF regulatory sequence." (PMID 33398073, 2021). "Whether neuroendocrine differentiation after ADT is related to upregulation of the NGF in prostate cancer is currently unclear." (PMID 33398073, 2021). "In addition, stimulation of mouse prostate cancer cells with nerve growth factor (NGF) upregulates the expression of Nav1.7, and in human prostate cancer cells, the promoter region of SCN9A (encoding Nav1.7) can be activated by NGF." (PMID 30895169, 2019). "Thus, prostaglandins, endothelins, bradykinin, colony-stimulating factors, TNF-α, TGF-β, PDGF, IL-1, nerve growth factor (NGF) and IL-6 are components of a ‘pro-inflammatory soup’ that sensitize nociceptors in prostate cancer-induced bone pain." (PMID 23918298, 2013). "In contrast, the mitogenic action of NGF on prostate cancer lines is mediated by TrkA." (PMID 24212627, 2011). "Furthermore, anti-NGF antibodies have been shown to reduce cell migration by up to 40% in two prostate cancer cell lines (DU-145 and PC-3), which have lost expression of p75NTR and retained TrkA tyrosine kinase activity." (PMID 24212627, 2011). "In the present study, we have examined 15 benign prostatic hyperplastic and 15 prostate cancer patients for the expression and localisation of beta-NGF by reverse transcription-polymerase chain reaction (RT-PCR), Western blotting, immunohistochemistry and ELISA." (PMID 8980402, 1996). "In addition, it was found that NGF participates in the neuroendocrine differentiation of prostate cancer since the inhibition or knockdown of NGF prevents neuroendocrine differentiation through a mechanism dependent on the cholinergic muscarinic receptor 4 (CHRM4)." (PMID 40243726, 2025). "Nerve growth factor, as a neurogenic signalling factor, may play an important role in the metastasis of many malignant tumours to bone, including breast cancer, oral squamous cell carcinoma and prostate cancer." (PMID 40860871, 2025). "To investigate whether NGF stimulation is associated with ZBTB46 after ADT, we examined prostate cancer samples consisting of tissue specimens collected from 18 prostate cancer patients before and after ADT at Taipei Medical University-Wan Fang Hospital (Taipei, Taiwan)." (PMID 33398073, 2021). "Therefore, targeting the NGF may have additional impacts of reducing malignant progression and bone pain in prostate cancer patients." (PMID 33398073, 2021). "It has been recognized that NGF and other neurotrophins regulate cell proliferation and invasion as well as cell death and survival, whereas dysregulation of neurotrophin signaling plays an important role in the pathogenesis of many tumors, such as breast and prostate cancer." (PMID 24988079, 2014). "NGF can interact with two receptors, TrkA and NGFR, which were found in several types of cancer, including prostate cancer; they both play a role in prostate cancer progression." (PMID 40243726, 2025). "In prostate cancer cells DU145 and PC3 with high expression of GPNMB, exogenous addition of nerve growth factor (NGF) can induce the regeneration of the NGF receptor P75NGFR, and P75NGFR is related to the degradation of cancer cells." (PMID 41180454, 2025). "This suggests potential alterations in NGF signaling in WERI-ETOR cells, considering that the pathogenesis of human proliferative diseases, such as prostate cancer, is similarly mediated by NGF signaling." (PMID 38339011, 2024). "In prostate cancer, the YAP1/TEAD complex mediates the occurrence of PNI by activating the transcription of the nerve growth factor NGF." (PMID 38567163, 2024). "They show that NGF interacts with the GPCR CHRM4, that both NGF and CHRM4 are upregulated in highly metastatic prostate cancer and that targeting NGF reduces therapy resistance in a mouse xenograft model." (PMID 33398073, 2021).
prostate carcinoma (continued). "The mean expression correlation was analyzed in prostate cancer datasets, which showed that CHRM4 was positively correlated with NGF, ZBTB46, and neuroendocrine marker expressions and inversely correlated with androgen-responsive gene expressions." (PMID 33398073, 2021). "Here, the authors discover that NGF, upregulated by transcription factor ZBTB46 in prostate cancer exposed to androgen therapy, promotes neuroendocrine differentiation." (PMID 33398073, 2021). "Thus, we discovered a mechanism of prostate cancer lineage plasticity that provides an effective prediction strategy utilizing gene expression-based biomarkers for NEPC development through the association of activated ZBTB46 and accumulated NGF via stimulation of the CHRM4–AKT–MYCN pathway." (PMID 33398073, 2021). "It appears that nerve growth factor (NGF) is produced by both stromal and epithelial tumor cells, but prostate cancer cells that produce autocrine NGF are able to escape paracrine dependence of stromal cell-derived NGF." (PMID 26042506, 2015). "For example, sodium current-targeting nerve growth factor was identified for prostate cancer cell lines, without distinguishing among subtypes." (PMID 39060933, 2024). "Although the role of NGF in prostate cancer has not been extensively studied, it is interesting to note that the p75 neurotrophin receptor (NTR) on cancer cells, to which all neurotrophins bind." (PMID 39429264, 2024). "YAP1 has the ability to bind with TEAD and recruit nerves by activating the transcription of the neural growth factor NGF, and research indicates a significant correlation between the occurrence of PNI in prostate cancer and the expression level of YAP1 in tumor tissues." (PMID 38567163, 2024). "In a recently published study analyzing the urinary NGF in patients with prostate cancer, the NGF was found to be predictive of the Gleason score, but the NGF was not correlated with PNI." (PMID 38791953, 2024). "The role of the NGF in prostate cancer has not been extensively studied." (PMID 38791953, 2024). "Since we showed that upregulated NGF cannot increase expression of CHRM1 and CHRM3, this result suggests that NGF–CHRM4 might be a unique signaling pathway involved in neuroendocrine differentiation of prostate cancer that differs from canonical acetylcholine–CHRM pathways." (PMID 33398073, 2021).
overactive bladder (37 papers, 2007 to 2026). Symptom of overactive detrusor muscle of the urinary bladder that contracts with abnormally high frequency and urgency. "As the nerve growth factor (NGF) was associated with overactive bladder symptoms and other bladder dysfunction, there was a need to analyze the expression levels of NGF and pro-NGF in the four groups." (PMID 38771415, 2024). "Patients with an overactive bladder (OAB) have been found to have increased mRNA levels of some urine biomarkers associated with inflammation (such as TNFα, IL2, NGF)." (PMID 41596750, 2026). "There was a decrease in night-time frequency, urgency, and levels of biomarkers for overactive bladder, such as nerve growth factor/creatinine and adenosine triphosphate/creatinine." (PMID 38004412, 2023). "Frequent detrusor contractions cause hypertrophy of detrusor muscles and therefore thickened detrusor wall in overactivity of bladder in OAB produces more NGF and measurement of BWTH." (PMID 35373950, 2022). "The cytokines with high diagnostic values to distinguish IC/BPS and overactive bladder included IL-10, RANTES, eotaxin, CXCL10, IL-12p70, NGF, IL-6, IL-17A, MCP-1, and IL-1RA." (PMID 35626252, 2022). "Otherwise, Liu and coworkers found that adult patients with overactive bladder who refract to anticholinergic therapy, present with high serum NGF and urinary NGF/Cr levels, and they remain high after subsequent other anticholinergic therapies." (PMID 35373950, 2022). "The findings of the current study suggested that NGF and associated purinergic signaling molecules were involved in BPAO-induced bladder overactivity." (PMID 34210091, 2021). "A couple of studies had demonstrated increased NGF levels on patients with overactive bladder and bladder inflammation." (PMID 32015355, 2020). "Both antimuscarinic agents and botulinum toxin, similarly to asiatic acid, diminish the urinary levels of BDNF and NGF in patients with bladder overactivity." (PMID 33584259, 2020). "In a rat model of cyclophosphamide-induced cystitis, HA was an effective treatment for bladder overactivity through the involvement of NGF signalling." (PMID 24614892, 2014). "Blockade of NGF using antibody against the NGF receptor prevents neural plasticity and bladder overactivity in experimental animals, suggesting that sequestration of NGF can reduce inflammation and improve OAB or pain symptoms." (PMID 23028581, 2012). "Although it is unclear at the moment if TRPV1 excitation enhances NGF release from urothelium, this neurotrophin was shown to induce bladder overactivity in experimental animals and was found in high amounts in the urine of OAB patients." (PMID 17561998, 2007). "Daytime symptoms suggestive of an overactive bladder may increase bladder wall thickness, and thus NGF levels may increase in the lower urinary system after denervation, inflammation and mechanical tension." (PMID 35373950, 2022). "Furthermore, urinary BDNF and NGF were examined as potential biomarkers for overactive bladder (OAB)." (PMID 35801157, 2022). "Bladder wall thickness measurements and NGF/Cr values, as noninvasive tools, could guide outcomes in the treatment of children with overactive bladder." (PMID 35373950, 2022). "The upregulation of NGF is closely related to an overactive bladder." (PMID 33562242, 2021). "Chronic BOO induced by BPH can stimulate NGF production, and this increase in NGF expression may be involved in bladder abnormalities and may positively correlate with the severity of overactive bladder." (PMID 30519263, 2018). "Recent studies showed that nerve growth factor (NGF) is a biomarker which could lead to overactive bladder (OAB) and interstitial cystitis or bladder pain." (PMID 27462520, 2016). "We have previously found that urinary nerve growth factor levels increased in patients with urolithiasis as well as in overactive bladder and IC/BPS, suggesting some inflammatory process might be involved in the urinary tract with urolithiasis." (PMID 25329457, 2014).
overactive bladder (continued). "Likewise, NGF expression in the voiding centers was also increased by stress urinary incontinence and overactive bladder." (PMID 24884998, 2014). "In addition, there was a significant difference between patients with IC/PBS and patients with overactive bladder (OAB) symptoms with respect to the urinary NGF and NGF/Cr levels (SMD = −0.62, 95%CI = −1.00–−0.24, P = 0.001 and SMD = −0.70, 95%CI = −1.01–−0.39, P<0.0001, respectively)." (PMID 25181532, 2014). "We chose to infuse NGF into the bladder wall for a two-week period (2.5 μg/μl) to determine if this route and duration of infusion, used for intrathecal administration, could also induce bladder overactivity." (PMID 17725832, 2007). "Increased responsive proinflammatory mediators (NGF, ICAM-1, COX-2, IL-1β, IL-6, TNF-α) likely contribute to bladder overactivity." (PMID 39941129, 2025). "Clinical research data have shown that urinary NGF levels are raised in multiple hyperactive bladder dysfunctions, such as IC/BPS and overactive bladder." (PMID 37275761, 2023). "Bladder wall thickness (BWTh) measurements and Nerve Growth Factor (NGF) /creatinine (Cr) values, as noninvasive tools, were found to predict daytime voiding problems in children with overactive bladder (OAB)." (PMID 35373950, 2022). "The evaluation tools consisted of POP-Q, urodynamic study, Overactive Bladder Symptom Score (OABSS), and urinary NGF." (PMID 34642384, 2021). "Secondary outcomes included Urine NGF level, Incontinence Impact Questionnaire (IIQ-7) and Urogenital Distress Inventory (UDI-6), as well as Overactive Bladder Symptom Score (OABSS)." (PMID 33062044, 2020). "NGF and BDNF are expressed in the urothelium and bladder smooth muscle, influencing lower urinary tract symptoms of overactive bladder (OAB) and IC/BPS." (PMID 24614892, 2014). "Using different urinary biomarkers including IL-10, RANTES, eotaxin, CXCL10, IL-12p70, NGF, IL-6, IL-17A, MCP-1, and IL-1RA, IC/BPS could be distinguished from overactive bladder." (PMID 36233356, 2022). "Using 200 ml as a cutoff value, we found that urinary NGF/Cr levels in OAB patients were significantly (P<0.05) higher than those found in the control group, but this difference disappeared in less severe forms of bladder overactivity." (PMID 23741373, 2013).